INS (insulin)
Diseases named in the same sentence as INS in open-access papers (continued):
Sharing a sentence is not in itself a finding about the gene and the disease.
gestational diabetes (continued). "For example, estrogens bind directly to INS, inhibiting binding to the INS receptor (IR), which may contribute to the observed variations in INS sensitivity observed during the menstrual cycle and also upon use of estrogen-containing birth control, as well as in gestational diabetes." (PMID 40003617, 2025). "Reduced caloric intake and lower gestational weight gain in women with NVP may enhance insulin sensitivity and reduce the risk of gestational diabetes, although current evidence does not confirm a direct causal relationship between NVP and a reduced incidence of gestational diabetes." (PMID 40566044, 2025). "Gestational Diabetes Mellitus (GDM) is a condition characterized by glucose intolerance during pregnancy, often due to insulin resistance induced by placental hormones." (PMID 40791233, 2025). "Gestational diabetes mellitus (GDM) is a serious obstetric complication that affects approximately 10% to 15% of pregnancies worldwide and is characterized by an insufficient insulin response to compensate for the insulin-resistant state of pregnancy." (PMID 38035802, 2024). "In a previous study performed by our group, pregnant women with Gestational Diabetes (GDM) showed higher vitamin D (VitD) levels in the last trimester, particularly in those requiring insulin." (PMID 39408904, 2024). "Gestational Diabetes Mellitus (GDM) represents a significant health concern during pregnancy, characterized by elevated blood glucose levels due to insulin resistance exacerbated by hormonal changes." (PMID 39219840, 2024). "Succinate levels rise before delivery in women with gestational diabetes mellitus (GDM), particularly those receiving insulin treatment." (PMID 38182909, 2024). "We aimed to test whether a voluntary, lightweight, once-weekly supervised exercise intervention, combined with advice to increase physical activity at home could prevent or delay the need for insulin in women diagnosed with gestational diabetes (GDM)." (PMID 39343942, 2024). "The purpose of this study is to examine the pregestational BMI value that results in insulin use in Japanese patients with gestational diabetes mellitus (GDM) and to assess whether the type of GDM treatment affects postpartum glucose tolerance." (PMID 39803116, 2024). "Another meta-analysis with 1119 study participants revealed that maternal probiotic supplementation lowered maternal serum glucose, insulin levels, and HOMA-IR indices but only in pregnant women with gestational diabetes mellitus." (PMID 39200093, 2024). "The objectives of this study were to determine the effect of vitamin-D supplementation on glycemic parameters: glucose levels in blood, insulin, HbA1c, HOMA-IR, and adiponectin in women with gestational diabetes." (PMID 39281255, 2024). "A study on walnut consumption in rats with gestational diabetes showed a decrease in FBG, gestational diabetes mellitus, and an increase in insulin and hepatic glycogen." (PMID 38628188, 2024). "The Metformin versus Insulin for the treatment of Gestational diabetes (MiG) study was an Australian off-label randomized trial including 751 women with GDM at 20 to 33 weeks of gestation to open treatment with metformin (373/751 patients) or insulin (378/751 patients)." (PMID 37409227, 2023). "The risk ratio for gestational diabetes mellitus was higher in women who needed insulin, regardless of their weight (risk ratio: 1.79; 95% confidence interval: 1.06–3.01) or whether they were overweight or obese (risk ratio: 1.77; 95% confidence interval: 1.28–2.45)." (PMID 37566567, 2023). "The study on gestational diabetes mellitus (GDM) mice showed that the pups demonstrated hypermethylation and epigenetic downregulation of IGF2 and H19 genes involved in insulin sensitivity." (PMID 37298715, 2023).
gestational diabetes (continued). "The findings of higher BMI and a more frequent history of GDM in a previous pregnancy in the insulin group agree with earlier reports that weight and history of GDM are related to the need for pharmacological treatment in women with gestational diabetes." (PMID 37268897, 2023). "However, we could not confirm a higher risk of needing insulin therapy in twin pregnancies with gestational diabetes based on monochorionic or dichorionic twin pregnancies." (PMID 37959321, 2023). "In humans, gestational diabetes mellitus (GDM) affects fetal insulin sensitivity." (PMID 36875483, 2023). "However, the trial included only a small sample of women with GDM (306/2,831), and it excluded women with GDM requiring insulin treatment or those with pregestational diabetes." (PMID 37691770, 2023). "Women with gestational diabetes mellitus (GDM) were classified into three subtypes according to the indexes of insulin sensitivity and insulin secretion." (PMID 36890429, 2023). "MD-based nutrition during pregnancy can help reduce the incidence of gestational diabetes, and pregnant women with GDM are less likely to require insulin therapy and have lower gestational weight gain." (PMID 37960204, 2023). "Other data show that prior to routine screening for gestational diabetes mellitus (GDM), exposure of the fetus to altered amniotic fluid glucose, insulin, and insulin-like growth factor-binding protein 1 has occurred." (PMID 37176607, 2023). "In other study performed on mice with gestational diabetes mellitus (GDM), OLE efficiently reduced blood glucose, insulin and alleviated oxidative stress and inflammation." (PMID 38203672, 2023). "Specifically, our interest focused on insulin since it is not only one of the most abundant human milk hormones, but it is also responsible for a significant disorder in pregnant women known as gestational diabetes mellitus (GDM)." (PMID 37191543, 2023). "According to subgroup analyses, gestational diabetes mellitus (GDM) appeared to have varied impacts on offspring BP by sex of offspring, region and economic level of family, published year, maternal insulin treatment status, and BP measurement." (PMID 36653821, 2023). "Gestational diabetes mellitus (GDM) is a common complication during pregnancy, characterized by the incapability of pancreatic beta cells to respond sufficiently to the increased insulin requirements of pregnancy leading to different degrees of hyperglycemia." (PMID 37522117, 2023). "Gestational diabetes mellitus (GDM) subtypes, which were identified by insulin sensitivity and insulin secretion, may have different mechanisms in causing LGA infants." (PMID 36890429, 2023). "Gestational diabetes mellitus (GDM) is a common obstetric metabolic complication where women without diabetes before pregnancy show increased glucose levels and insulin resistance during pregnancy." (PMID 36558427, 2022). "Physiologic insulin resistance could be noted in normal pregnancy, and gestational diabetes mellitus (GDM) may develop due to inadequate adaptation of insulin secretion." (PMID 36726471, 2022). "Continuing the history of previous diseases, she also had mild gestational diabetic mellitus (GDM) since 5th month of pregnancy and had been under treatment with 6‐unit of insulin detemir." (PMID 36483858, 2022). "Eligible studies should have compared the maternal, perinatal and neonatal outcomes between pregnant women with gestational diabetes mellitus (GDM) managed by intermediate acting (NPH) and by long-acting insulin analogues." (PMID 36271431, 2022). "Notably, for patients with pregestational diabetes and gestational diabetes mellitus (GDM), the dominating pharmacotherapy is insulin, while only metformin and glyburide are used in some countries." (PMID 35909556, 2022).
gestational diabetes (continued). "Gestational diabetes mellitus (GDM) results from pregnancy-induced changes in maternal glucose metabolism and insulin sensitivity whereby demand for insulin production on the mother’s pancreas increases as pregnancy grows." (PMID 35794524, 2022). "During some pregnancies, this may lead either to dysfunction of the β-cells due to excessive secretion of insulin or insufficient compensation of the blood glucose load, or both, which will ultimately result in gestational diabetes mellitus (GDM)." (PMID 35408874, 2022). "Non-modifiable risk factors include a strong family history of T2DM in first- or second-degree relatives, offspring of pregnancy complicated by gestational diabetes mellitus (GDM), minority race/ethnicity, and the physiologic insulin resistance of puberty." (PMID 37990723, 2022). "Among the most common pregnancy complications is gestational diabetes mellitus (GDM), defined as an increase in blood sugar (glucose) level during pregnancy due to insulin resistance or insufficient insulin production." (PMID 34867825, 2021). "In a mouse model study, Cur improved gestational diabetes mellitus (GDM)-related complications by significantly reducing blood glucose, insulin and total oxidative stress." (PMID 34356370, 2021). "Various studies have shown that the expression of miR-195-5p in the serum of patients with gestational diabetes mellitus (GDM) is a key factor in the pathogenesis of GDM, which may be related to insulin resistance regulation." (PMID 34658906, 2021). "Gestational diabetes mellitus (GDM) impairs fetal insulin sensitivity." (PMID 34621244, 2021). "Most of the studies on insulin and IGF-1 levels are focused on women with gestational diabetes, with a primary focus on maternal health and newborn parameters." (PMID 34371854, 2021). "The percentage increase in insulin dosage after ANC administration was similar for women with type-1, type-2 and gestational diabetes." (PMID 33600450, 2021). "In human pregnancy complicated with gestational diabetes mellitus, MAGE was inversely correlated with early-phase insulin secretion and with HOMA-IR, which represents insulin resistance." (PMID 33627830, 2021). "Gestational diabetes mellitus (GDM) may appear in the second or third trimester of pregnancy, when insulin insensitivity is normally increasing." (PMID 34911968, 2021). "In conclusion, the present study demonstrates that high glucose and insulin levels of the GDM environment decrease DHA transport through the trophoblasts via decreased SIRT1-mediated signaling, providing a molecular mechanism linking gestational diabetes and decreased transplacental DHA transport." (PMID 32365792, 2020). "Interestingly, many of these alterations in cellular insulin sensitivity return to normal in the postpartum state, however if any of them become exaggerated, gestational diabetes mellitus (GDM) develops." (PMID 32977673, 2020). "Gestational diabetes mellitus (GDM) is a pathological condition, characterized by glucose intolerance or hyperglycemia resulted from insufficient insulin production or signaling in pregnant women." (PMID 32802120, 2020). "The current standard for treatment of hyperglycemia in women with pre-gestational diabetes (PGDM) involves intensive insulin therapy; occasionally, oral hypoglycemic agents, a change of diet, and close monitoring of blood glucose are recommended in women with T1D, T2D, or GDM." (PMID 32867274, 2020). "Gestational Diabetes Mellitus (GDM) is characterized by abnormal maternal D-glucose metabolism and altered insulin signaling." (PMID 33232364, 2020). "Gestational diabetes (GDM) occurs when pregnant women have dysfunctional β-cells, unable to balance the increased requirements of insulin." (PMID 32545151, 2020). "Gestational diabetes and T2DM have the similar pathological characteristics, both of them have an insulin-resistant state related with some chronic inflammation." (PMID 32946041, 2020).
gestational diabetes (continued). "In the “MET in Gestational diabetes” (MiG) trial, pregnant women with GDM were randomly assigned to receive either insulin or MET (plus insulin if required)." (PMID 33381040, 2020). "This means that changes in the lipid profile pattern precede the onset of GDM and could play a major role in the insulin resistance states of gestational diabetes mellitus." (PMID 31836012, 2019). "The Metformin in Gestational Diabetes (MiG) trial, randomising women with GDM to metformin (+/− insulin if needed) or insulin, suggested that metformin might affect infancy fat deposition patterns." (PMID 31396660, 2019). "As observed, the groups represent three diabetic conditions, and these are non-insulin dependent (NID), insulin-dependent (IND) and gestational diabetes (GTD)." (PMID 31652912, 2019). "A K-mean assessment was used to cluster the instances, after 12 iterations the instances classified out of 3022: 2662 (88.09%) non-insulin dependent (NID), 176 (5.82%) insulin-dependent (IND) and 184 (6.09%) gestational diabetes (GTD)." (PMID 31652912, 2019). "In the short term, in women with gestational diabetes mellitus (GDM) requiring drug treatment, glibenclamide is clearly inferior to both insulin and metformin, while metformin (plus insulin when required) performs better than insulin." (PMID 29508275, 2018). "In gestational diabetes mellitus (GDM), it was shown that knockdown of miR-503 enhanced insulin secretion of pancreatic β-cells, promoted cell proliferation, and protected cells from apoptosis." (PMID 30305865, 2018). "We collected maternal and neonatal anthropometric data (n = 49) in normoglycemic healthy lean, obese or obese with gestational diabetes mellitus women, as well as determined UCB leptin and insulin concentrations by ELISA." (PMID 27440187, 2016). "The Telemedicine for Gestational Diabetes Mellitus (TeleGDM) trial aims to explore the use of telemedicine in supporting care and management of women with GDM treated with insulin." (PMID 27507708, 2016). "In a previous study, insulin and SHBG levels in cord blood were likewise inversely related among mothers with gestational diabetes." (PMID 27462374, 2016). "Gestational diabetes mellitus (GDM), a disorder in glucose and insulin metabolism, is one of the most common complications in pregnancy." (PMID 23577256, 2013). "To this aim, we retrospectively studied pregnancies in women with type 2 and gestational diabetes mellitus (GDM) when ILPS or NPH insulin was added to MNT and/or rapid insulin analogues." (PMID 23840206, 2013). "Both ß-cell mass and insulin secretion are increased and the threshold for glucose-stimulated insulin secretion is decreased during pregnancy, and insufficiency in such responses can lead to the development of gestational diabetes mellitus (GDM)." (PMID 22928026, 2012). "We have previously demonstrated that placental MDR1, MRP2 and BCRP mRNA expression is elevated in rat dams with streptozotocin-induced gestational diabetes mellitus (GDM) but nearly normal in rat dams with streptozotocin-induced GDM whose blood glucose was normalized following insulin treatment." (PMID 22558111, 2012). "We recently demonstrated that osteocalcin, a marker of bone remodeling, is higher in women with gestational diabetes (GDM) compared to women with normal glucose tolerance during pregnancy [CON] and related to enhanced insulin secretion in these women." (PMID 22844418, 2012). "His mother had gestational diabetes (GDM) during pregnancy which was treated with insulin." (PMID 23101555, 2012). "When combined, the eight observational cohort studies consisted of a total of 702 women with pregestational and/or gestational diabetes, of whom 331 received insulin glargine and 371 received NPH insulin." (PMID 22685467, 2012).
gestational diabetes (continued). "This study aimed to compare the plasma glucose concentrations and serum insulin, leptin and adiponectin in cord blood of babies of women (a) without gestational diabetes mellitus (GDM), (b) with mild GDM under routine care, or (c) mild GDM with treatment." (PMID 17430602, 2007). "Inhibition of nitric oxide synthase affected only fetal vessel segments from the control group or diet-controlled gestational diabetes group, but not from insulin-dependent gestational diabetes." (PMID 39384641, 2025). "In addition, AsIV also reduced inflammatory genes IL-6 and TNF-α and suppressed NACHT, LRR, and PYD domain-containing protein 3 (NLRP3) inflammasome-related proteins in the pancreas of gestational diabetes mellitus (GDM) mice, leading to lower blood glucose and insulin levels." (PMID 41011612, 2025). "Gestational diabetes mellitus (GDM) is a metabolic disorder characterized by impaired glucose regulation during pregnancy, primarily due to progressive insulin resistance (IR) and inadequate compensatory insulin secretion." (PMID 40564970, 2025). "The pathomechanisms of diet-controlled and insulin-treated gestational diabetes are not well-understood." (PMID 39384641, 2025). "Insulin is the first-line treatment for gestational diabetes, but metformin and glibenclamide are not." (PMID 39963668, 2025). "Gestational diabetes (GD) is a heterogeneous disorder that arises when pancreatic insulin secretion fails to compensate for the insulin resistance of pregnancy." (PMID 41246123, 2025). "In an HFD-induced gestational diabetes rat model, berberine increased serine phosphorylation of IRS-1 in hepatic tissue, elevated the p-AKT/AKT ratio, and improved fasting blood glucose and insulin resistance indices." (PMID 41471379, 2025). "This was also observed with glucagon, where FABP4 promotes hepatic glucose production irrespective of insulin, particularly in women with gestational diabetes mellitus (GDM)." (PMID 38731797, 2024). "Although there are no data for fetuses and infants, reduced insulin sensitivity, characterizing gestational diabetes mellitus, stimulates the activity of this enzyme in adult female animals and humans." (PMID 39519317, 2024). "Insulin alone is not superior than metformin with or without insulin on gestational diabetes mellitus." (PMID 39669300, 2024). "Prenatal care was monitored throughout the pregnancy, with negative serologies (STORCH), and the mother reported insulin use close to delivery due to gestational diabetes." (PMID 39766813, 2024). "We recently reported that, amongst women who remained normoglycaemic after gestational diabetes mellitus, South Asian women had lower hepatic insulin clearance (HIC) and lower insulin secretion relative to insulin resistance compared with their Nordic counterparts." (PMID 38786765, 2024). "The aim of this study is to assess the use of metformin with or without insulin for the treatment of Gestational Diabetes Mellitus compared to insulin alone." (PMID 39669300, 2024). "Not much is currently known about disturbances in insulin signaling and glucose transport in leukocytes of women with gestational diabetes mellitus (GDM) during and after pregnancy." (PMID 39684804, 2024). "However, 1 to 25% of all pregnant women develop gestational diabetes GDM, which, if left unregulated, exposes the fetus to prolonged periods of elevated hormones such as insulin and IGF, as well as increased circulating carbohydrates and fatty acids." (PMID 39690358, 2024). "Additionally, we also observed significantly decreased levels of high density lipoprotein, insulin and HOMA-IR (p = 0.0001**) in all thetrimesters of gestational diabetes mellitus subjects." (PMID 37814679, 2023). "The doe is diagnosed with gestational diabetes mellitus when it begins to show elevated glucose levels, namely in cases where insulin resistance is not compensated by sufficient insulin production." (PMID 37888574, 2023).